IL1B (interleukin 1 beta)
Diseases named in the same sentence as IL1B in open-access papers (continued):
Sharing a sentence is not in itself a finding about the gene and the disease.
ZIKV infection (continued). "Results from an immunofluorescence study illustrated that ZIKV infection activated intracellular production of IL-1β, and this ZIKV-induced IL-1β production was almost completely reduced in ZIKV-infected THP-1 macrophages with AP treatment." (PMID 36559293, 2022). "Previous studies have shown that ZIKV infection activates the NLRP3 inflammasome, which leads to processing of pro-caspase-1 and secretion of IL-1β in infected monocytic cell lines, PBMC, or monocyte-derived macrophages." (PMID 35446851, 2022). "In conclusion, this study demonstrated that acute ZIKV infection during pregnancy triggers overexpression of the growth factor GDF3 and the inflammasome-related factors NLRP3, IL-1β, and IL-18." (PMID 35632746, 2022). "ZIKV infection promoted muscle lesions, with infiltration of inflammatory cells, along with an upregulation of proinflammatory cytokines (TNF, IL-1β, and IL-6) and chemokines (RANTES and MCP-1) involved in monocyte/macrophage recruitment (39, –, 41)." (PMID 34468171, 2021). "Microglia and activated astrocytes produce several inflammatory mediators, including IL-1β, TNF, glutamate, nitric oxide (NO) among others, which can trigger neuronal death after ZIKV infection." (PMID 34335614, 2021). "Even both of them induced apparent liver inflammation, ZIKV infection showed a more severe inflammatory response than DENV-2 infection based on the inflammation scores and the gene expression levels of IL-1β, TNF, IL-6, and TGFβ-2 in liver." (PMID 31191474, 2019). "ZIKV infection activated NLRP3 inflammasome and triggered the production of IL-1β in the kidney, which directly decreased the expression of aquaporins, thus leading to the water re-absorption disorder." (PMID 31474993, 2019). "ZIKV infection triggered the inflammatory response and renal cell injury by activating Nod-like receptor 3 (NLRP3) inflammasome and secreting interleukin-1β (IL-1β)." (PMID 31474993, 2019). "ZIKV infection activated NLRP3 inflammasome in HK-2 cells, which indicated by the increased expression level of NLRP3, ASC, cleaved-caspase-1, pro-IL-1β and mature IL-1β." (PMID 31474993, 2019). "The pro-IL-1β, TNF-α, IL-8, and MCP-1 mRNAs were induced by LPS, ZIKV genomic RNA, HCV genomic RNA, and ZIKV infection." (PMID 29317641, 2018). "The survival rates of mice were reduced by ZIKV infection, and to our surprise, all infected mice survived in the presence of Ac-YVAD-cmk, further confirming that Casp-1 or IL-1β is important for the infection of ZIKV." (PMID 29317641, 2018). "Major elevation was observed for IL-1β and IFN-α in acute phase ZIKV infection was observed in SIV-ZIKV co-infected RMs." (PMID 30359380, 2018). "We show that the immune response during the acute phase of ZIKV infection is polyfunctional and broadly inflammatory, as evidenced by significantly elevated levels of IL-4, IL-17, IFN-γ, IL-1β, IL-1Ra, TNF-α, and IL-6 in patients as compared to controls." (PMID 29768624, 2018). "The body weights of infected mice were reduced during ZIKV infection, and such reductions were attenuated by Ac-YVAD-cmk, suggesting that Casp-1 or IL-1β is important for the infection of ZIKV." (PMID 29317641, 2018). "Here we reveal a mechanism by which ZIKV infection induces host inflammatory responses by facilitating the NLRP3 inflammasome assembly and IL-1β secretion." (PMID 29317641, 2018). "The high concentrations of IL-1b and CXCL8 in the CVL after ZIKV infection suggest that enhanced neutrophil recruitment is a major response to ZIKV replication in the FRT." (PMID 28746373, 2017). "Thus, it is possible that ZIKV infection could activate neuronal production of TNFα and IL-1β." (PMID 28878777, 2017). "Additionally, IL-1β is a pro-inflammatory cytokine crucial in inflammatory responses during SARS-CoV-2 and zika virus infections." (PMID 40431570, 2025).
ZIKV infection (continued). "Using a qRT-PCR assay, high expression levels of pro-inflammatory cytokine genes, including IL6, IL15, IFNγ, TNFα, CXCL15, IL18, and IL1β, were confirmed in ZIKV-infected placentas, suggesting that ZIKV infection may trigger placental inflammation." (PMID 41263557, 2025). "While ZIKV infection of microglia in Ifnar1−/− mice did not lead to microglial activation, infection of macrophages resulted in the induction of IL-1β." (PMID 37191498, 2023). "Thus, ZIKV infection of THP-1 cells activates the NLRP3 inflammasome and consequently induces IL-1β maturation and secretion." (PMID 37191498, 2023). "Serum samples from pregnant (n = 18) and non-pregnant (n = 22) women with acute ZIKV infection were assessed for NLRP3, IL-1β, IL-18, and GDF3 markers through an enzyme-linked immunosorbent assay." (PMID 35632746, 2022). "Similar patterns of mRNA expression were also observed for TNF-α, IL-1β, IL-8 and CXCL-10 (IP-10) cell models following ZIKV infection; however, with a much higher level of IP-10 expression observed in the ZIKV-susceptible HASTR/ci35 cells compared with the ZIKV-resistant CCF-STTG1 cells." (PMID 35053142, 2022). "In addition, ZIKV infection increases the amounts of neurotoxic cytokines, i.e., TNF and IL-1β, in neuronal cultures and blockade of these factors suppresses neuronal cell death." (PMID 33658344, 2021). "Studies have reported a greatly increased expression levels of IL-1β and IL-18 in the serum of patients infected with ZIKV, indicating that inflammasomes may be activated by ZIKV infection and involved in tissue damage." (PMID 31474993, 2019). "The intercellular cell adhesion molecule (ICAM-1) a cell surface receptor that can be up regulated by IFNγ, IL1β and TNFα in SCs51 showed increased mRNA expression during culture but was not modulated by ZIKV infection." (PMID 31289325, 2019). "The results obtained in the present study indicate that ZIKV infection induces neuroinflammation in microglia which leads to the production of IL-6, TNF-α, IL-1β and IFNs, molecules with strong pro-inflammatory effects that feature among the most potent neuroinflammatory cytokines." (PMID 30359409, 2018). "ZIKV infection during pregnancy triggers maternal immune activation (MIA) at the maternal-fetal interface, with placental immune and trophoblast cells producing a range of proinflammatory cytokines and chemokines, such as IL-1β, IL-6, TNF-α, and type I interferons." (PMID 41044062, 2025). "Additionally, we established that cross-reactive DENV antibodies enhance ZIKV infection in KU812 cells, which is selectively coupled to enhanced chemokine ligand 5 (CCL5), interleukin 1β (IL-1β), and C-X-C motif chemokine ligand 10 (CXCL10) secretion and inhibited granzyme B (GrB) secretion." (PMID 35862953, 2022). "We do not know whether lower levels of IL-1β, IL-6, IL-8, IL-10, IL-12, IL-13, IL-17A, TNF, and IFN-γ in ZIKV offspring at 32 days were caused by subclinical in utero ZIKV infection or maternal cytokine background." (PMID 31725819, 2019). "ZIKV infection induced a clear antiviral immune response in these cells as shown by the production of high levels of IFN-α, IFN-β and IFN-γ, as well as neurotoxic factors such as TNF-α, IL-1β and IL-6 during the first hours of infection with maximum levels at 48 hpi." (PMID 30359409, 2018). "In addition, serum IL-1β was found in nonpregnant patients with ZIKV infection." (PMID 36559293, 2022). "Moreover, in A129 mice, ZIKV infection significantly induces IL-1β production in the brain, spleen, liver and kidney, but such inductions are significantly suppressed by the caspase-1 inhibitor (Ac-YVAD-cmk), confirming that Casp-1 is required for ZIKV-induced activation IL-1β." (PMID 29317641, 2018). "IL-1β mRNA expression and protein secretion were activated by ZIKV but not by inactivated ZIKV, indicating that ZIKV infection is required for the NLRP3 inflammasome activation." (PMID 29317641, 2018).
ZIKV infection (continued). "Notably, when we measured IL-1β+ populations of ZIKV+ versus ZIKV– for both microglia and macrophages, IL-1β + population of ZIKV+ macrophages but not ZIKV+ microglia, was significantly increased by ZIKV infection, indicating that ZIKV-infected macrophages are the source of IL-1β in the brain." (PMID 37191498, 2023). "ZIKV infection induced in nonpregnant women significantly higher levels of the anti-inflammatory cytokine IL-10, and increased pro-inflammatory cytokines IL-6, IL-2, IFN-α, and IFN-γ, and decreased levels of IL-1β in relation with uninfected, nonpregnant women." (PMID 33430059, 2021). "Interestingly, ZIKV infection did not appear to be markedly cytotoxic or inflammatory based on a lack of obvious damage to the VEC multilayers and no change in pro-inflammatory cytokine levels including IL-8 and IL1β that are commonly upregulated in inflamed vaginal samples." (PMID 30692980, 2018).
breast tumor (53 papers, 2011 to 2025). "Previous studies have established that IL-1β expression in breast tumors of all subtypes is associated with increased migration and metastatic potential 28,29,41." (PMID 39801513, 2024). "This approach is particularly relevant in our study because TNFα and IL-1β were found to be expressed persistently in breast tumors, to exert powerful and causative tumor-promoting roles, and to be significantly associated with poor prognosis in patients." (PMID 33806906, 2021). "IL-1β is an inflammation-associated cytokine secreted mainly by macrophages localized in the breast tumor microenvironment, whose overexpression is thought to be tumor-promoting in many cancer models." (PMID 28234914, 2017). "Likewise, high IL1β levels within the breast tumor microenvironment have been associated with a high tumor grade and an invasive cancer phenotype." (PMID 32778144, 2020). "Patients whose breast tumors overexpress IL-1β have been found to have higher rates of recurrence and metastasis." (PMID 41007766, 2025). "The scaffolds’ composition facilitated normal breast cells’ viability and proliferation, while the presence of PTX into the scaffolds’ compositions stimulated caspase-1 activity, IL-1β secretion, and ROS production by the breast tumor cells." (PMID 39940603, 2025). "One report noted coordinated over-expression of TNF-α, IL-1β, and chemokines (CCL2, CCL5) in breast tumors, which was associated with epithelial–mesenchymal transition (EMT) and invasive behavior." (PMID 41007766, 2025). "Although other sources of NLRP3 are possible, this study showed a clear induction of IL-1β production in myeloid cells by breast tumor cells." (PMID 35631400, 2022). "Here, we expanded upon those findings by using genetic and pharmacological NLRP3 inhibition to elucidate NLRP3 as the predominate inflammasome sensor responsible for breast tumor-induced IL-1β production in infiltrating myeloid cells." (PMID 35631400, 2022). "For poorly differentiated breast tumors, an increase in the content of IL-1β, IL-2, IL-6, and IL-10 was observed, while the content of the rest decreased compared to the control group, but to a lesser extent than for highly differentiated tumors." (PMID 36286034, 2022). "Our previous studies have shown that antibody-mediated IL1β inhibition or genetic ablation of IL1β in mice results in significantly reduced bone metastasis but increased growth of primary breast tumours in xenograft and allograft models, respectively." (PMID 36230739, 2022). "Direct interaction between breast tumour cells and osteoblasts promoted IL-1β release from both cell types, which enhanced the progression of EMT, invasion, migration, angiogenesis, and bone colonization." (PMID 36307871, 2022). "In contrast to the dormancy-inducing effect of LIF, CXCL12 and Gas6, the inflammatory cytokine IL-1β promoted tumour proliferation and subsequently triggered overt metastasis of breast tumour cells." (PMID 36307871, 2022). "Although IL-1β released upon activation of inflammasomes is known to induce tumor progression, it also has a tumor suppressive function in the breast tumor microenvironment." (PMID 33686176, 2021). "In agreement with such differential effects of IL-1β, blockade of its receptor (IL-1R), in combination with paclitaxel, slightly reduced primary breast tumor growth, but potentiated pulmonary metastasis." (PMID 33686176, 2021). "Accumulating evidence suggests that antigen-presenting cells, such as dendritic cells and macrophages, are primarily responsible for releasing IL-1β in the breast tumor microenvironment." (PMID 33686176, 2021). "In view of the continuous presence of TNFα and IL-1β together in many luminal-A breast tumors, we began this study by determining the impact of TNFα + IL-1β stimulation on the morphology of stimulated MSCs." (PMID 33806906, 2021).
breast tumor (continued). "In the model of breast tumor mice, EA significantly reduced the level of inflammatory cytokines including IL-1β and TNF-α and increased the level of the anti-inflammatory cytokine, IL-10, in serum." (PMID 35095910, 2021). "It has long been established that there is IL-1β protein expression within human breast tumor samples." (PMID 32635472, 2020). "In our study, we have used potent and most clinically relevant pro-inflammatory cytokines - TNFα and IL-1β - that are expressed in breast tumors and have pro-metastatic functions in TNBC." (PMID 31031757, 2019). "Last, we show that tamoxifen (Tam) is significantly more effective as first-line therapy for malignant ER+ breast tumors if combined with IL1β and PDGF-BB receptor blockers." (PMID 31419632, 2019). "IL-1B is also involved in the mobilisation of MDSCs further promoting both primary and metastatic breast tumours." (PMID 29760166, 2018). "In particular, IL-1B upregulates OPG via p38 and p42/22 MAPK signalling pathway and induces OPG secretion, which also associates with macrophage infiltration in primary breast tumours." (PMID 29760166, 2018). "IL-1β is up regulated in breast neoplasm initiation and development and also IL-1R and IL-1β variations have been related to breast tumorigenesis." (PMID 30447690, 2018). "In this review, we discuss how IL-1B from both the tumour cells and the tumour microenvironment influence growth of primary breast tumours, dissemination into the bone metastatic niche and proliferation into overt metastases." (PMID 29760166, 2018). "Encouraged by these in silico findings, we sought to verify the expression of IL-1β in patient material from different breast tumor subtypes and compare this with asporin expression." (PMID 26327350, 2015). "In this report, we found that metastatic breast tumour cells in the brain highly expressed IL-1β which then ‘activated’ surrounding astrocytes." (PMID 23495140, 2013). "While the expression of CCL2, CCL5, TNFα or IL-1β was only minimally detected in infiltrating leukocytes of all groups of patients, the four factors were clearly observed in breast tumor cells, with mainly a cytoplasmic staining pattern." (PMID 21486440, 2011). "The inter-connection between CCL2 & CCL5 and TNFα & IL-1β in the immune setting suggests that similar interactions exist between these chemokines and cytokines also within the inflammatory context of breast tumors." (PMID 21486440, 2011). "IL-1β and IL-6 expression is increased in the early stages of breast malignancies and is positively correlated with advanced tumor stages, indicating a critical role in breast tumor metastasis." (PMID 40035822, 2025). "Obesity enhanced NLRC4 expression in tumor-infiltrating CD11b+ cells in breast tumors in mice, resulting in activation of IL-1β, and promotion of disease progression through adipocyte-mediated expression of vascular endothelial growth factor A and angiogenesis." (PMID 35739593, 2022). "IL1b negativity is a prognostic survival factor in breast tumors." (PMID 35203471, 2022). "Because IL-1B displays opposite functions in primary breast tumour and bone metastasis, its role in metastatic breast cancer may be tissue-specific." (PMID 34290237, 2021). "In addition to dendritic cells, other types of immune cells also have potential to release IL-1β in the breast tumor microenvironment." (PMID 33686176, 2021). "Moreover, IL-1β is upregulated in breast neoplasm initiation and development, while IL-1R and IL-1β variations have also been related to breast tumorigenesis." (PMID 32635472, 2020). "Altogether, these results show that the IL-1β production by the hypoxic TNBC cells may trigger a paracrine feed-forward signaling that stimulates malignant features in main components of the breast tumor microenvironment as CAFs." (PMID 32778144, 2020).